STAT3 (signal transducer and activator of transcription 3)
Diseases named in the same sentence as STAT3 in open-access papers (continued):
Sharing a sentence is not in itself a finding about the gene and the disease.
cancer (continued). "Autologous primary prostate cells or cancer cell lines were inhibited by silencing STAT3 and IL-6 signaling using fludarabine, a STAT3 inhibitor, and tocilizumab, an IL-6 inhibitor." (PMID 39202020, 2024). "The use of decoy inducer-PROTAC conjugates to induce protein degradation against oncogenic transcription factors such as STAT3 represents an innovative approach to cancer therapy." (PMID 38773495, 2024). "The concurrent elevation of JAK1 and STAT3 contributed synergistically to activating the p-STAT3 signaling pathway, subsequently increasing cancer cell proliferation and metastasis." (PMID 39136000, 2024). "Accumulating evidence has shown that STAT3 activation plays an important role in the growth and maintenance of GSCs by increasing the expression of major cancer stemness markers, including CD133, Sox2, Oct4, Nanog, ALDH1A1, and integrin α6." (PMID 38474197, 2024). "STAT3 is valuable as a prognostic biomarker because it is correlated with cancer prognosis, drug resistance, and immune mechanisms." (PMID 38834900, 2024). "Accumulated evidence has clearly shown that activation of STAT3 facilitates cancer invasion and metastases and induces cancer-promoting inflammation, thus inhibiting immune response." (PMID 38338065, 2024). "Accumulating evidence shows that STAT3 and NF-κB cooperate to promote the development and progression of various cancers." (PMID 38856747, 2024). "The role of STAT3 inhibitors in treating SQSTM1-ALK fusion-positive cancers, as well as the combination of ALK and STAT3 inhibitors, warrants further investigation." (PMID 39555099, 2024). "Luteolin can induce cancer-cell apoptosis by promoting Tyr705- and Ser727-phosphorylated STAT3 degradation." (PMID 38474604, 2024). "The upregulation of SHC1 activated immune-associated and cancer-related pathways, such as epithelial-mesenchymal transition, interferon-gamma response, inflammatory response, and the IL6/JAK/STAT3 pathway." (PMID 38763954, 2024). "STAT3 is a transcription factor that plays a prominent role in tumorigenesis, making it a valuable target for cancer interception." (PMID 39273033, 2024). "STAT3 (signal transducer and activator of transcription 3) is a key transcription factor involved in cancer progression and metabolism." (PMID 39597836, 2024). "Cancer cachexia involves a variety of pathways, with STAT3 activation being a key factor in skeletal muscle wasting as observed in animal models of cancer cachexia." (PMID 38807976, 2024). "The JAK2/STAT3 pathway possesses oncogenic functions, including promoting cell growth, enhancing migratory ability, and inducing drug resistance in cancer cells." (PMID 38661644, 2024). "STAT3 activation is a well-established molecular mechanism to suppress cellular apoptosis, and STAT3 activation is upregulated in many immortalized cancer cell lines." (PMID 39484717, 2024). "Differentially expressed genes (DEG) were selected (|log2FC|≥1, P<0.05), and their enriched signaling pathways were identified, showing that KLF7 regulated several signaling pathways associated with cancer, including MAPK/ERK, RAS, JAK/STAT3, and PI3K/AKT." (PMID 38164176, 2024). "Irisin has also been shown to regulate phosphatidylinositol 3-kinase (PI3K)/protein kinase B (AKT) and signal transducer and activator of transcription 3 (STAT3)/Snail pathways that are involved in cancer cell growth, proliferation, survival, and migration." (PMID 38671861, 2024). "Activated STAT3 signaling is known to regulate essential cancer cell mechanisms such as proliferation, survival, and metastasis pathways by modulating genes involved in cell proliferation (PCNA), the cell cycle (Cyclin D1), and apoptosis (PARP and Caspase 3)." (PMID 39273033, 2024). "Overexpression and persistent activation of STAT3 have been correlated with poor patient prognosis in various types of cancers (including breast, ovarian, pancreatic, lung, and colon cancer)." (PMID 39200368, 2024).
cancer (continued). "Western blot analysis was performed to evaluate the pharmacodynamic markers involved in cell proliferation, apoptosis, cancer stem cells (CSCs), and STAT3 signaling in BCa." (PMID 39273033, 2024). "Enterotoxigenic B. fragilis was confirmed to facilitate the progress of CAC by activating signal transducer and activator of transcription 3 (STAT3), which in turn stimulates the growth and reproduction of cancer cells." (PMID 39683442, 2024). "Recently, studies reported a close correlation between STAT3 and abnormal upregulation of specific lncRNAs in these cancers." (PMID 38172648, 2024). "The inhibitors of JAKs are successfully used in the treatment of cancer and immune-mediated diseases, suggesting that indirect inhibition of STAT3 is a promising approach." (PMID 39305962, 2024). "Aberrant methylation of the CpG of SOCS3 promoters has been reported to result in increased phosphorylation and activation of STAT3 in cancers such as lung cancer and hepatocellular carcinoma." (PMID 38534772, 2024). "In the past decades, several studies have shown that CD44 and STAT3 cooperate with each other in cancer promotion." (PMID 38385088, 2024). "Conversely, STAT3 has been correlated with cancer cell survival, angiogenesis, and evasion of immune surveillance." (PMID 38886756, 2024). "STAT3 is an important transcription factor of various signaling pathways in human malignant tumors and participates in many processes in cancer occurrence and development, such as cancer cell growth, cell cycle, anti-apoptosis effects, and immune evasion." (PMID 39202965, 2024). "Signal transducer and activator of transcription 3 (STAT3) plays a crucial role in several cellular processes and is aberrantly activated in many cancers." (PMID 38326371, 2024). "In cancer and wound healing, STAT3 directly targets and upregulates CCDC88A, which also enhances the activation of STAT3 via a positive feedback loop." (PMID 38630692, 2024). "The protein known as Signal Transducer and Activator of Transcription 3 (STAT3) has emerged as a significant focus for cancer therapy, primarily because of its involvement in the development of tumors and the progression of malignancy." (PMID 38535455, 2024). "The activated STAT3 directly binds to the gene promoter of CALB2 and regulates CALB2 transcription, indicating that IL6-STAT3 inflammatory signaling is responsible for CALB2 upregulation in cancer cells." (PMID 39358777, 2024). "Conversely, our results suggest that the inhibition gp130 and downregulation of STAT3 subsequent to the exposure to both pomace extracts, especially blueberry pomace, can enhance antiproliferative and antimetastatic effects in cancer cells." (PMID 39200479, 2024). "It was reported that inhibition of CK2 hinders STAT3 signaling and decreases aggressive phenotypes in multiple cancer types." (PMID 38318383, 2024). "Co-overexpression of IL-6 and phosphorylated STAT3 (pSTAT3) is commonly observed in breast cancer and other cancer types." (PMID 39451730, 2024). "As mentioned, STAT3 plays a crucial role in maintaining stemness and self-renewal of cancer stem cells (CSCs) in CRC." (PMID 38185635, 2024). "We also highlight that STAT3 signaling regulates the Warburg effects, fatty acid oxidation, and amino acid metabolism of cancer cells." (PMID 38245798, 2024). "Recently, numerous studies have indicated that overly activated JAK/STAT signaling promotes the proliferation, migration, and invasion of cancer cells in CC, whereas the inhibition of JAK2/STAT3 signaling suppresses cancer progression." (PMID 38673975, 2024). "Given its significant role in cancer progression, researchers are focusing on developing STAT3 inhibitors for cancer treatment." (PMID 39598398, 2024). "Multiple studies have confirmed that STAT3 is hyperactivated in most human cancers, is activated in many solid and hematological tumors and is associated with poor clinical outcomes." (PMID 38486162, 2024).
cancer (continued). "Noninvasive STAT3 imaging can help determine the cancer status and predict the efficacy of STAT3 inhibitors." (PMID 38834900, 2024). "In the pancreatic cancer model, blocking the recruitment of TAM by activating STAT3 will also reduce the number of cancer stem cells." (PMID 38693304, 2024). "GSTM1 can also activate STAT3 signaling, a key modulator of multiple cellular processes including proliferation, apoptosis, and metastasis, which is altered in multiple types of cancers." (PMID 39726707, 2024). "PD-L1 overexpression on macrophages induced via STAT3 activation by cancer cell-derived GM-CSF was suggested to promote cancer progression in lung adenocarcinoma in vitro and vivo animal models." (PMID 38659003, 2024). "Aberrant activation of STAT3 is common in cancer, promoting cell survival and resistance to apoptosis." (PMID 39594587, 2024). "As dictated earlier, IL-6 activates STAT3 signaling to help cancer cells achieve their proliferative potential." (PMID 38279220, 2024). "The studies have, furthermore, demonstrated that morusin acts on several different pathways, inhibiting NF-kB translocation and suppressing STAT3 signalling pathways, leading to the reduced invasion of SK-Hep1 cancer cells." (PMID 38892365, 2024). "More importantly, EGFR, AKT1, and STAT3 are well-known biomarkers of cancer, but the effects of genistein on these targets remain elusive." (PMID 38731403, 2024). "Based on accumulating evidence, STAT3 is a target gene downstream of AKT/mTOR signaling in cancer cells." (PMID 38183094, 2024). "For instance, Th17 markers (STAT3) are upregulated in cancers and STAT3 signaling often inhibits antitumor immunity and promotes apoptosis resistance." (PMID 39328506, 2024). "A paracrine loop between cancer cells and TAMs, whereby TAM derived IL-6 activates STAT3/GLUT3 pathway in cancer cells to preserve high CXCL8 levels was suggested." (PMID 39044824, 2024). "Since cucurbitacin I exhibits an antitumor effect, cucurbitacin I and JAK2/STAT3 inhibitors have received increasing attention as potential cancer therapeutic agents." (PMID 39255287, 2024). "Accordingly, the inhibition of inflammation promoting cancer is anticipated by targeting key mediators and/or regulatory factors (such as NF‐κB and STAT3) of inflammatory pathways and cytokines (e.g., IL‐1, TNF, and IL‐6)." (PMID 38766879, 2024). "IL-6 and IL-22, two cytokines that activate STAT3, enhanced XIAP in cancer cells, and such induction was attenuated in SMAD7-deficient cells." (PMID 39001432, 2024). "YAP/TAZ can be recruited by STAT3/JUNB, mediating downstream cellular transformation associated with poor cancer survival." (PMID 39738726, 2024). "The findings from this study provide valuable insights into the mechanism of STAT3 degradation and its potential as a target for cancer therapy." (PMID 38773495, 2024). "We further describe evidence supporting the overexpression and aberrant activation of STAT3 in different cancers." (PMID 38339245, 2024). "STAT3 is an important mediator that controls the cancer environment and promotes cancer development, as well as a favourable target for the anticancer immune response." (PMID 38618181, 2024). "On the other hand, the JAK/STAT3 signaling pathway is important in cancer stemness research as it can link ncRNA and m6A in tumorigenesis and metastasis." (PMID 39136000, 2024). "Therefore, further analysis of the regulation of other oncogenic signals and cancer-associated transcription factors via PRMT5 induced by STAT3 should provide insights into the molecular mechanisms underlying the oncogenic functions associated with the PRMT5/STAT3 activation loop." (PMID 38760429, 2024). "Silymarin and its primary bioactive flavonolignan, silibinin, inhibit PD-L1 in cancer cells by suppressing STAT3 signaling." (PMID 38594256, 2024).
cancer (continued). "Functionally, Th17 cells can induce an inflammatory response associated with EMT, angiogenesis, and metastasis through mechanisms involving STAT3 activation and interaction with cancer stem cells." (PMID 39683528, 2024). "On the one hand, STAT3 shows highly activated in most cancers and cardiac injuries and is demonstrated to be a pathogenic regulator." (PMID 38495094, 2024). "As a transcription factor, STAT3 is essential in differentiated tissue functions during vertebrate development, inflammation, immune control, and cancer." (PMID 39734345, 2024). "In murine cancer models, B7H4 and its function-enhancing oesophageal precancerous lesions have been associated, at least in part, with IL-6/STAT3 activation." (PMID 39061159, 2024). "These cancer-promoting factors are under the control of two important transcription regulatory pathways, NF-kB and STAT3." (PMID 39451241, 2024). "STAT3 signaling participates in cancer promotion by regulating glycolysis, oxidative phosphorylation, ROS production, and lipid and glutamine metabolisms in both cancer cells and other cells in the tumor microenvironment." (PMID 38338457, 2024). "Collectively, these findings suggest that betalains have significant anticancer potential, demonstrating effects such as apoptosis induction, the inhibition of cancer cell proliferation, and the modulation of key signaling pathways like NF-kB and Stat3/Sox2." (PMID 39682981, 2024). "This is likely because STAT3 dysfunction contributes to cancer cell proliferation, survival, drug resistance, metastasis, and immune evasion." (PMID 39200368, 2024). "Strategies to inhibit the JAKs/STAT3 pathway prove instrumental in mitigating immune tolerance in cancer cells, with tangible outcomes observed in restraining tumor invasion and growth in xenografts." (PMID 38646539, 2024). "TAMs are an important source of IL-6, which regulates the expression of m6A regulators and activates the JAK2/p-STAT3 pathway in cancer cells." (PMID 38872221, 2024). "This stimulates the signal transducer and activator of transcription 3 (STAT3) to initiate downstream signals involved in anti-apoptotic, angiogenic, proliferative, invasive, metastatic, and drug-resistant processes in cancer cells." (PMID 38806553, 2024). "Targeting STAT3 is a therapeutic approach for cancer, inhibiting tumor growth and enhancing antitumor immunity." (PMID 39104501, 2024). "A-FABP enhances IL6/STAT3 signal transduction, promoting cancer growth and metastasis by regulating the NF-κB/miR-29b pathway." (PMID 39192979, 2024). "FGFR inhibitors have been approved for the treatment of various cancers and a STAT3-dependent regulation of FGFR4 has been documented in the H.pylori infected intestinal GC." (PMID 37945798, 2024). "Growing evidence has exhibited that acetylated-STAT3 can boost its transcriptional activity via facilitating their access to the DNA template, and finally promote cancer metastasis." (PMID 38560562, 2024). "Cancer cells often activate inflammatory signaling pathways, such as NF-κB, STAT3, and COX-2, which can lead to increased tumor growth and resistance to cell death." (PMID 38474160, 2024). "Signal transducer and activator of transcription (STAT3) plays a key role in all steps of carcinogenesis, from cancer onset to cancer survival and progression." (PMID 38534772, 2024). "Niclosamide decreases STAT3 transcriptional activity by preventing STAT3's phosphorylation and nuclear translocation in different cancer cells." (PMID 39191850, 2024). "Research indicates that both transducer and activator of transcription 3 (STAT3) and cellular‐Myc (c‐Myc) are highly expressed in the malignant tumors." (PMID 38800967, 2024). "This, in turn, activates Src and STAT3, two well-known factors in maintaining the tumorigenicity and stemness of cancer cells, propelling malignant transformation." (PMID 38977663, 2024). "Then, IL-6 binds to IL-6R on the surface of cancer cells to induce STAT3 axis for cancer progression." (PMID 39014491, 2024).
cancer (continued). "EGFR induces PD-L1 via the IL-6/JAK1/STAT3 pathway 63, which reciprocally drives PD-L1 phosphorylation (Tyr112) to evade cancer immunosurveillance." (PMID 38505617, 2024). "STAT-3, a transcription factor involved in cellular proliferation and invasion, plays a significant role in cancer progression." (PMID 39767693, 2024). "Signal transducer and activator of transcription (STAT) proteins are a cytoplasmic transcription factor family, and among them, STAT3 plays a key role in angiogenesis and is highly activated in most cancers." (PMID 39596828, 2024). "NCTD also promotes the expression of miR-214, thereby inhibiting the β-catenin pathway and STAT3 pathway, exerting anti-cancer effects." (PMID 38803433, 2024). "The search results indicate that STAT3 plays a critical role in regulating ferroptosis in various cancer types and other diseases." (PMID 39834804, 2024). "STAT3 inhibitors have shown promise in suppressing the growth of various cancers while also targeting inflammation." (PMID 39598398, 2024). "Along this line, the reduction or inhibition of STAT3 in cancer cells decreases NRF2 expression, its transcriptional activity, and antioxidant capacity." (PMID 38755517, 2024). "In this study, we found that STAT3 can induce PRMT5 expression, suggesting that cancer-promoting functions of PRMT5 other than STAT3 activation are involved in the oncogenic function of STAT3." (PMID 38760429, 2024). "Previous studies demonstrated that the NSAIDs celecoxib and ibuprofenS14 as well as aspirinS15 reduce STAT3 phosphorylation in cancer cells." (PMID 38302863, 2024). "It has been reported that abnormal expression of STAT3 has significant correlation with poor overall survival of cancer patients." (PMID 38303001, 2024). "Differently from 5-AZA, the inhibition of the EZH1/2 histone methyltransferase by DS-3201, reported to contribute to STAT3 activation in other cancers, slightly affected STAT3 phosphorylation or survival in PEL cells, either alone or in combination with AG490." (PMID 38534772, 2024). "Inflammation can directly promote cancer growth and development by generating a wide array of inflammatory molecules and biomarkers, including NFκB, hypoxia-inducible factor-1α, STAT3, and pro-inflammatory molecules such as TNF-α, IL-1β, IL-6, and IL-23." (PMID 38671861, 2024). "In cancer cells, negative regulators are inhibited, so the STAT3 pathway remains active which results in cancer progression." (PMID 38892394, 2024). "Therapeutic strategies aimed at inhibiting JAK-STAT signaling, including STAT3 decoy oligonucleotides, which compete with endogenous STAT3 for DNA binding, have shown promise in preclinical models of cancer." (PMID 39483536, 2024). "The intricate network of STAT3 interactions underscores its critical role in maintaining immune homeostasis, with evidence suggesting that its dysregulation plays a role in cancer." (PMID 39294673, 2024). "STAT3 is inactive in unstimulated cells, but is constitutively activated in cancer cells, including HCC cells." (PMID 38163874, 2024). "It has been previously informed that abnormal activation of STAT3 induce oncogenic processes in various cancers such as prostate, lung, ovary, leukemia, and breast." (PMID 38310190, 2024). "These immunoblots clearly show that BP1003 significantly reduces the protein levels of STAT3 and its downstream targets, which play critical roles in cancer progression." (PMID 39200368, 2024). "These M1-like TAMs promote EMT and cancer stem cell formation through the IL-6/Jak/Stat3/THBS-1 axis." (PMID 39200273, 2024). "STAT3 phosphorylation blockage led to the induction of cancer programmed cell death and an earlier arrest in the G0-G1 phase of the cell cycle." (PMID 39125943, 2024). "The findings reveal a novel mechanism where H3K23ac/TRIM24 mediates EGFR-induced STAT3 activation, enhancing the oncogenic potential of the EGFR/STAT3 pathway in human cancer." (PMID 39160596, 2024).